NOS2 (nitric oxide synthase 2)
Diseases named in the same sentence as NOS2 in open-access papers (continued):
Sharing a sentence is not in itself a finding about the gene and the disease.
Arthritis (8 papers, 2005 to 2024). Inflammation of a joint. "Surprisingly, certain genes implicated in arthritis pathogenesis were more than 2-fold higher in arthritic V-KO joints, including NOS2, IL-23a, and IFNA1." (PMID 29216931, 2017). "These potentially include NO production via rhythms in Nos2 expression and rhythmic MMP3 production, both previously linked to arthritis-associated joint damage and regulation of inflammation, as well as other inflammation-associated disease effectors (Cxcl5, Ccl20, Mmp13, Rankl/Tnfsf11)." (PMID 38981514, 2024). "Studies have found that Nos2-induced NO promotes mannose-induced Ps and PsA models (MIP) in mice, and Nos2-dependent IL-1α is essential for arthritis development by promoting IL-17 production of innate lymphoid cells." (PMID 38035065, 2023). "MC3R knockdown with serum transfer-induced arthritis exacerbated significant bone erosion, high expression of RANKL in the joint, increased time of NF-kB activation, and upregulation of proinflammatory genes [IL-1β, IL-6, and nitric oxide synthase 2 (NOS2)]." (PMID 35874704, 2022). "The upregulated expression of TNF-α, IL-1α, IL-1β, IL-4R, P-selectin, MIP-1α (CCL3), MCP-1 (CCL2), NOS2 and NOS3 demonstrated in the present study is in agreement with previous observations of the dependency of the rat SCW-induced arthritis model on these mediators." (PMID 15642130, 2005).
COVID-19 (8 papers, 2020 to 2025). A disease caused by infection with severe acute respiratory syndrome coronavirus 2. "The same study stated that NOS2 is significantly upregulated in patients with severe and critical COVID-19 compared with healthy controls." (PMID 37893073, 2023). "Under our experimental conditions, instead, IL-6, despite its well-recognized correlation with COVID-19 severity, was completely ineffective, excluding the role of this cytokine in NOS2 induction." (PMID 37893073, 2023). "Our findings sustain the therapeutic efficacy of this drug in COVID-19 since, besides limiting the cytokine storm, it also prevents NOS2 induction." (PMID 37893073, 2023). "Recent evidence points to the induction of inducible nitric oxide synthase (NOS2/iNOS) as a component of inflammatory response since NOS2 is upregulated in critical COVID-19 patients." (PMID 37893073, 2023). "al, reported higher levels of the NOS2 gene (coding for iNOS, one of the enzymes catalyzing nitric oxide production) in severe and critical COVID-19 cases compared to controls." (PMID 36121875, 2022). "In particular, our analysis newly identified targets such as NOS2, F2, and REN, which are mechanistically relevant to COVID-19 pathogenesis." (PMID 41471341, 2025). "The potential mechanism of action of HXZQ for COVID-19 is inhibiting SARS-CoV-2 replication, improving immune, and anti-inflammatory, mainly by acting on 3CLpro, PTGS2, AR, HSP90AB1, CAMSAP2, PPARG, NOS2, and other targets." (PMID 36388945, 2022). "During the period of COVID-19, HLJDD was also found to play a therapeutic role in COVID-19 through regulating multiple signaling pathways based on targeting genes such as IL6, IL10, MMP9, NOS2, VEGF, and TGFβ1." (PMID 35127697, 2021). "Additionally, the anti-CHOL/COVID-19 effect of VA was controlled by 3 core genes, including ICAM1, NOS2, and CAT, suggesting the possible therapeutic and immunotherapeutic targets for treating COVID-19 or CHOL/ COVID-19." (PMID 34176789, 2021). "Furthermore, six core gene targets including CAT, NOS2, CXCR3, MAPK1, GPT, and ICAM1 of VA against CHOL/COVID-19 were identified using Cytoscape tool." (PMID 34176789, 2021). "Moreover, the expression of ICAM1, NOS2, and CAT was increased in CHOL/COVID-19, while the survival rate was low, although these genes were only marginally increased." (PMID 34176789, 2021).
diabetic retinopathy (8 papers, 2009 to 2022). "Similarly, VNTR variation in the promoter of nitric oxide synthase 2 (NOS2) alter expression and is associated with diabetic retinopathy." (PMID 24023707, 2013). "The inhibitor of Nos2 has been reported to inhibit the development of diabetic retinopathy through reducing retinal microaneurysms, acellular capillaries and pericyte ghosts." (PMID 36557283, 2022). "Importantly, diabetic Cd40−/− mice are protected from retinal upregulation of intercellular adhesion molecule 1 (ICAM-1), TNF-α, IL-1β, nitric oxide synthase 2 (NOS2) and C-C motif chemokine ligand 2 (CCL2) and do not develop diabetic retinopathy." (PMID 35920844, 2022).
influenza (8 papers, 2018 to 2025). An acute viral infection of the respiratory tract, occurring in isolated cases, in epidemics, or in pandemics; it is caused by serologically different strains of viruses (influenzaviruses) designated A, B, and C, has a 3-day incubation period, and usually lasts for 3 to 10 days. "It is known that influenza and other pathogenic viruses induce the nitric oxide synthase 2 (NOS2) to cause the formation of an excess of NO in tissues and peripheral blood, and conversion of the latter into the nitroperoxide anion (ONOO•) under oxidative conditions." (PMID 36498864, 2022). "Additionally, we noted that increased IFN-β correlated with increased CCL2, CXCL1 and nitric oxide synthase (NOS2) expression in the lungs, which has been associated with severe influenza infections." (PMID 34691044, 2021). "Pulmonary edema has been associated with the endogenous activity of nitric oxide synthase 2 (NOS2) in various models and clinical cases of lung injury, including hypercalcemia, endotoxin treatment, influenza, and ARDS (98, –, 101)." (PMID 35980186, 2022). "Nitric oxide synthase 2 (NOS2) is one of the inflammatory mediators shown to cause epithelial cell damage and thereby lead to morbidity in influenza-infected mice that present with hypercytokinemia." (PMID 34691044, 2021). "A study of juvenile mice that exhibit severe disease in response to influenza infection revealed recruitment of inflammatory monocytes with high expression of inducible nitric oxide synthase (NOS2), which induces apoptosis of epithelial cells." (PMID 34691044, 2021). "The ORNs-d-М injection for prevention and treatment of the influenza infection reduced the mRNA level of nos2, arg2, and xdh expression in comparison with the virus-infected mice." (PMID 30037133, 2018). "Further, these M1/M2 cells had increased expression levels of both Arg1 and Nos2 in Stat2−/− mice during influenza-bacterial super-infection." (PMID 30337919, 2018). "The pathogenic role of RNIs and ROSs during influenza virus infection realizes by increasing the enzyme activity of NOS, XO, and mRNA expression of nos2 and xdh in influenza-infected lungs." (PMID 30037133, 2018). "Importantly, during influenza infection, the primary source of NOS2 has been demonstrated to be inflammatory monocytes." (PMID 34691044, 2021). "Second, NOS2-/- mice survived infection with a low pathogenicity virus strain via an IFN-γ-dependent anti-viral mechanism, demonstrating that NOS2 contributed more to influenza-mediated pneumonitis rather than viral control in WT mice." (PMID 34691044, 2021). "Next, we found increased gene expression of Nos2 and Arg1 in Stat2−/− mice when compared to WT mice during influenza, but not MRSA infection." (PMID 30337919, 2018).
parasite infection (8 papers, 2012 to 2024). "In addition, NOS2-deficient animals, in contrast to ifn-γ KO mice, can survive if treated with suboptimal doses of benzonidazole during peak of parasitemia even if the drug is withdrawn after parasite control." (PMID 22348160, 2012). "Interestingly, despite high nitric-oxide synthase activation (NOS-2), parasitemia and mortality in CKO mice were increased compared with infected WT mice." (PMID 37908369, 2023). "The existence of macrophages co-expressing Nos2 and Arg1 genes, exerting immunosuppressive phenotype, has also been described in other parasite infections such as Trypanosoma cruzi or Giardia lamblia, as well as during bacterial Mycobacterium tuberculosis infection." (PMID 36420267, 2022). "Genetic variants of interest identified in several immune related genes for all the antibody response and parasitic infection traits: IBDV (TOLLIP, ANGPTL5, BCL9, THEMIS2), MDV (GRM7), SG (MAP3K21), Eimeria (TOM1L1), and cestodes (TNFAIP1, ATG9A, NOS2)." (PMID 33193617, 2020). "We followed parasitemia in animals treated with NOS2 inhibitors after parasitemia was controlled and we did not observe recrudescence of parasite proliferation." (PMID 22348160, 2012). "As NOS2, LRG-47 and ARG1 expression by macrophages was unaltered in vivo in IL-22−/− mice and IL-22 did not influence parasite killing by macrophages in vitro, the fact that the parasitemia was unaffected by the absence of IL-22 was not surprising." (PMID 27650379, 2016).
lymphoma (7 papers, 2014 to 2025). A malignant (clonal) proliferation of B- lymphocytes or T- lymphocytes which involves the lymph nodes, bone marrow and/or extranodal sites. "With a lymphoma mouse model, the anti-tumor effect mediated by adoptively transferred CD8+ T cells is dependent on nitric oxide synthase 2 (NOS2) expressed by Tip-DCs." (PMID 34359674, 2021). "Activated MDSC express high amounts of arginase-1 and NOS2, and inhibitors of both enzymes (L-NMMA for NOS2 and norNOHA for arginase-1) reversed MDSC suppressive mechanisms in MM and lymphoma models." (PMID 25538893, 2014). "Activated MDSCs express high amounts of arginase 1 and NOS2, and inhibitors of both enzymes (L-NMMA for NOS2 and nor NOHA for arginase-1) reversed MDSC suppressive mechanisms in MM and lymphoma models." (PMID 31640764, 2019).
myocardial infarction (7 papers, 2013 to 2025). Gross necrosis of the myocardium, as a result of interruption of the blood supply to the area, as in coronary thrombosis. "Colchicine is predicted to play a significant role in cardiac fibrosis and myocardial infarction, with a score greater than 0.5 as a tubulin antagonist, beta-tubulin antagonist, and NOS2 inhibitor." (PMID 39200761, 2024). "More recently, rosuvastatin has been shown to reverse isoproterenol-induced acute myocardial infarction in the rat, at least partly related to up-regulation of NOS2." (PMID 28727746, 2017). "In heart tissue from myocardial infarction mice, the expression of the M1 marker nitric oxide synthase 2 (NOS2) was substantially upregulated compared with that of the control group, while the expression of the M2 marker interleukin-10 was significantly downregulated." (PMID 38102663, 2023). "Aerobic exercise inhibits cardiac sympathetic nerve sprouting, restores β3-AR/β1-AR balance and increases β3-AR expression through the activation of NOS2 and NOS1 after myocardial infarction." (PMID 24842290, 2014).
periodontitis (7 papers, 2013 to 2024). An acute or chronic inflammatory process that affects the tissues that surround and support the teeth. "In addition, our ligature-induced model confirmed the distinguished bone resorption and the pro-inflammatory gene expression of IL-1β, TNF-α, CCL-2, Nos2, IL-17 and IL-6, which were highly enhanced during the progress of the early acute phase of new periodontitis." (PMID 38069063, 2023). "This study showed that treatment in the periodontitis model significantly reduced the expression of genes (COX-2, NOS-2, INF-γ, OSCAR and TGFβ)." (PMID 38918842, 2024). "The molecular docking results showed that BBR can effectively bind to periodontitis targets ALOX5, AKT1, NOS2, and TNF, indicating that these four targets have high biological activity and can serve as potential biomarkers and key therapeutic targets for BBR treatment of periodontitis." (PMID 38704553, 2024).
Anxiety (6 papers, 2019 to 2024). Intense feelings of nervousness, tension, or panic often arise in response to interpersonal stresses. "(Casp1, Ifngr, Nos2)−/− mice displayed decreased levels of depressive- and anxiety-like behaviour while exhibiting increased locomotor activity and moving velocity." (PMID 31015500, 2019). "Moreover, (Casp1, Ifngr, Nos2)−/− mice displayed decreased levels of anxiety-like behaviour in the elevated plus maze, as they spent more time in the open arms of the maze compared to wt mice." (PMID 31015500, 2019).
cervical cancer (6 papers, 2015 to 2024). A primary or metastatic malignant neoplasm involving the cervix. "In contrast, venetoclax can interact with the NOS2 protein and has a good inhibitory binding effect on NOS2, making it a potential drug for reducing NOS2 expression in cervical cancer tumor cells." (PMID 38062129, 2024).
heart failure (6 papers, 2012 to 2025). Inability of the heart to pump blood at an adequate rate to meet tissue metabolic requirements. "Considering that IFN-γ has antifibrotic properties and TNF-α is involved in fibrosis, the synergistic effect of the two cytokines on NOS2 expression may have contributed to the development of heart failure." (PMID 22811738, 2012). "On the other hand, a positive correlation was observed between the number of IFN-γ-positive and NOS2-positive cells, irrespective of the occurrence of heart failure (P = 0.02)." (PMID 22811738, 2012). "Cells positive for NOS2 were present in 10 of the 11 cases with heart failure and in 6 of the 10 cases without heart failure." (PMID 22811738, 2012). "TNF-α may also contribute to the development of heart failure through apoptosis and the induction of NOS2, producing nitric oxide which exerts strong negative inotropic effects." (PMID 22811738, 2012).
hepatocellular carcinoma (6 papers, 2012 to 2023). A malignant tumor that arises from hepatocytes. "In hepatocellular carcinomas, NOS2 is a Wnt β-catenin/Tcf-4 target gene that promotes tumorigenesis." (PMID 37346068, 2023). "In fact, patients with hepatocellular carcinoma (HCC) display high levels of NO derivates in serum and tumors associated with increased NOS2 and NOS3 expression." (PMID 34200849, 2021). "NOS2 has been also found to be upregulated in hepatocellular carcinoma (HCC), and is often increased in the hepatocytes of patients with chronic hepatitis and alcoholic cirrhosis, conditions that predispose to HCC." (PMID 30234010, 2018). "However, NO generated by the inducible NOS (iNOS or NOS2) and the co-expression of iNOS with mitochondrially encoded cytochrome c oxidase II (MT-COII or COX2) may lead to a particularly aggressive cancer phenotype of breast, liver, colon, pancreatic ductal adenocarcinoma, and hepatocellular cancers." (PMID 36831498, 2023).
multiple sclerosis (6 papers, 2009 to 2022). A progressive autoimmune disorder affecting the central nervous system resulting in demyelination. "Recently, astrocytic activation of cPLA2 bound directly with MAVS enhanced NF-ĸB pathways to produce proinflammatory factors such as Ccl2 and Nos2 in an animal model of multiple sclerosis (MS)." (PMID 35705959, 2022). "The role of NO was identified in differentiation and functions of Th cells, as NOS2-deficient mice were found to harbor enhanced frequency of Th17 cells with the reduction in Tregs cells in EAE, a mouse model of multiple sclerosis, indicating that NO is suppressed in Th17 cells differentiation." (PMID 31164892, 2019).
brain tumor (5 papers, 2017 to 2024). "A selective inhibitor of NOS2 is 1400 W (PubChem ID: 1433), which could inhibit U87MG cells (brain tumor cell)." (PMID 35216171, 2022).
endometriosis (5 papers, 2005 to 2025). The growth of functional endometrial tissue in anatomic sites outside the uterine body. "Immunoblot analysis revealed NOS2 protein expression exclusively in the macrophages of the patients with endometriosis." (PMID 40227209, 2025). "Peritoneal macrophages in women with endometriosis have increased NOS2 expression and NO production compared to healthy women, which can be further exacerbated after LPS stimulation, and in mice elevated NO inhibits embryo implantation." (PMID 35358206, 2022).
Hepatic steatosis (5 papers, 2014 to 2026). Steatosis is a term used to denote lipid accumulation within hepatocytes. "These components, especially 11-deoxyalisol A and 8β-methoxyatractylenolide I, alleviated hepatic steatosis by downregulating NOS2 and PLA2G2A expression." (PMID 42075812, 2026). "Furthermore, there was a reduction in the extent of hepatic steatosis, triglyceride content, and the expression of Nos2, the M1 marker." (PMID 41259454, 2025). "Besides, Trim26 ablation did slightly elevate Cebpd-Hif1a signalling and its corresponding downstream pathways, including Cebpd, Hif1a, Nos2, p-p38, and p-p65 protein, in HFHC- and WTDF-induced fatty liver and NASH serum-treated AdTRIM26- or AdshTRIM26-transfected L02 cells." (PMID 37821436, 2023).
pneumonia (5 papers, 2017 to 2022). An acute, acute and chronic, or chronic inflammation focally or diffusely affecting the lung parenchyma, caused by an infection in one or both of the lungs (by bacteria, viruses, fungi, or mycoplasma.). "Besides, reduced expression of NOS2 by alveolar macrophages was found in preterm human neonates with fulminant early-onset pneumonia, a disorder that is associated with ascending intrauterine infection." (PMID 36078100, 2022). "Upregulation of the IFN-γ responsive genes Nos2 and Cxcl9 during pneumonia were confirmed by RT-qPCR in independent samples." (PMID 28900269, 2017). "Effect of RYNM on serum IL-10, NOS2, COX-1, IL-6, TNF-α and NF-κB levels in pneumonia model rats (mean ± S.D., n = 10)." (PMID 33678123, 2021).
cardiac hypertrophy (4 papers, 2010 to 2022). "Indeed Nos3 KO mice just like triple Nos1, Nos2, Nos3 KO mice develop cardiac hypertrophy." (PMID 35874523, 2022). "Early cardiac hypertrophy induced by angiotensin II did not change either NOS1 or NOS2 mRNA expressions (not illustrated), NOS3 mRNA expression or NOS3 protein expression." (PMID 21151982, 2010). "NOS1 and NOS2 may also slightly prevent cardiac hypertrophy since hypertrophy is significantly higher in triple KO mice in comparison to Nos3 KO mice, however, Nos1 or Nos2 KO mice do not develop cardiac hypertrophy." (PMID 35874523, 2022).
cholestasis (4 papers, 2016 to 2024). Impairment of the bile flow caused by obstruction within the liver, or outside the liver in the bile duct system. "Arginase 1 (Arg1) and nitric oxide synthase 2 (NOS2), which was contributed to neutrophils immunosuppressive by inhibiting T cells activation, were significantly upregulated in cholestasis liver metastasis." (PMID 38951890, 2024). "CXCL8, NOS2, and IL-6 reportedly play a role in inflammation, hyperalgesia, cholestasis, and neoplastic cell transformation." (PMID 35720847, 2022). "This, together with the fact that no expression of NOS-2 was detected in our experimental model of cholestasis, suggests that NOS-3 regulation by AP-1 is a key process involved in the hepatocellular damage during cholestasis." (PMID 27490694, 2016).
Chronic colitis (4 papers, 2013 to 2026). A chronic inflammatory disease of the large intestine (colon, cecum and rectum). "In contrast, reduced long-term inflammatory damage to the colon has been identified in NOS2 knockout mice in a trinitrobenzene-induced chronic colitis model." (PMID 36830680, 2023). "In contrast, NOS2 knockout mice demonstrated reduced long-term inflammatory damage to the colon when compared to wild-type mice in a trinitrobenzene-induced chronic colitis model." (PMID 36830680, 2023). "TLR4 triggers elevated production of prostaglandin E2, influences epidermal growth factor receptor signaling (EGFR), and increases TNF-α/NOS2 induction in chronic colitis." (PMID 28408791, 2017).